XPA (XPA, DNA damage recognition and repair factor)
Description:
Involved in DNA nucleotide excision repair (NER). Initiates repair by binding to damaged sites with various affinities, depending on the photoproduct and the transcriptional state of the region. Required for UV-induced CHEK1 phosphorylation and the recruitment of CEP164 to cyclobutane pyrimidine dimmers (CPD), sites of DNA damage after UV irradiation. During NER stimulates the 5'-3' helicase activity of XPD/ERCC2 and the DNA translocase activity of XPB/ERCC3. Connects XPD/ERCC2 and XPB/ERCC3 during NER, retaining DNA near the XPB/ERCC3 active site, and stabilizing the complex in a different conformation than in transcribing TFIIH.
Synonyms: XPAC; XP1
Tractability: Small molecule: a structure with a bound ligand is known. PROTAC: UniProt records ubiquitination sites on it; ubiquitination databases record sites on it; a small molecule that binds it is known.
Target class: Other nuclear protein
Gene: Protein-coding gene on chromosome 9 (97,674,909 to 97,697,340, reverse strand). Ensembl gene ENSG00000136936.
Subcellular location: Nucleus
Subcellular location (Human Protein Atlas): Nuclear bodies; Cytosol; Nucleoplasm
Pathways (Reactome):
DNA Repair: Dual Incision in GG-NER; Dual incision in TC-NER; Formation of Incision Complex in GG-NER; Formation of TC-NER Pre-Incision Complex
Gene Ontology:
Molecular function: damaged DNA binding; protein binding; protein domain specific binding; protein homodimerization activity; sequence-specific double-stranded DNA binding
Biological process: DNA repair; nucleotide-excision repair; protein localization to nucleus; UV protection; base-excision repair; nucleotide-excision repair involved in interstrand cross-link repair; nucleotide-excision repair, DNA damage recognition; UV-damage excision repair
Cellular component: DNA replication factor A complex; nuclear body; nucleoplasm; nucleus; nucleotide-excision repair factor 1 complex
Genetic constraint (gnomAD): Loss-of-function variants: 22 observed, 29.42 expected, observed/expected ratio (o/e) 0.75, 90% interval 0.53 to 1.07. The upper end of that interval is the gene's LOEUF score, 1.07, which puts it in group 4 of 6, group 1 being the genes least tolerant of losing a copy. Missense variants: 314 observed, 288.02 expected, observed/expected ratio (o/e) 1.09, 90% interval 0.99 to 1.2. Synonymous variants: 122 observed, 103.08 expected, observed/expected ratio (o/e) 1.18, 90% interval 1.02 to 1.38.
Gene-disease validity (ClinGen):
ClinGen rates the evidence that XPA causes each of these diseases.
xeroderma pigmentosum group A (autosomal recessive): Definitive. Any xeroderma pigmentosum in which the cause of the disease is a mutation in the XPA gene.
Homologues: Orthologues: chimpanzee XPA (99% identical), macaque XPA (97% identical), dog XPA (93% identical), pig XPA (91% identical), guinea pig XPA (85% identical), mouse Xpa (84% identical), rat Xpa (74% identical), tropical clawed frog xpa (68% identical), rabbit XPA (65% identical), zebrafish xpa (57% identical), Drosophila melanogaster Xpac (43% identical), Caenorhabditis elegans xpa-1 (34% identical).
Diseases named in the same sentence as XPA in open-access papers:
XPA is named in the same sentence as 93 diseases in open-access papers, as found by Europe PMC text mining. Sharing a sentence is not in itself a finding about the gene and the disease. The quoted sentences say what the papers report.
xeroderma pigmentosum (77 papers, 2005 to 2026). Xeroderma pigmentosum (XP) is a rare genodermatosis characterized by extreme sensitivity to ultraviolet (UV)-induced changes in the skin and eyes, and multiple skin cancers. "It is mainly caused by variants in eight different genes: xeroderma pigmentosum complementation group A (XPA) through complementation group G (XPG)." (PMID 40072281, 2025). "Xeroderma pigmentosum is an autosomal recessive condition caused by mutations in XPA-XPF genes that are involved in nuclear excision repair of DNA damaged by UV radiation." (PMID 40687210, 2025). "Homozygous pLoF variants in the gene XPA are known to cause a related phenotype, xeroderma pigmentosum, which is characterized by extreme vulnerability to UV radiation and childhood-onset skin cancer." (PMID 36653560, 2023). "Xeroderma pigmentosum (XP) represents the most common hereditary cutaneous DNA damage syndrome and is caused by mutations in proteins of the nucleotide excision repair (XPA-XPG)." (PMID 34381458, 2021). "Xeroderma pigmentosum is autosomal recessive caused by mutations in different genes (XPA-XPG) involved in NER (GGR), further enhancing malignant transformation." (PMID 34381458, 2021). "The XPA (xeroderma pigmentosum group A) gene, also known as XP1 and XPAC, encodes the XPA protein, which is a DNA damage recognition and repair factor." (PMID 34540891, 2021). "Xeroderma pigmentosum (XP) is caused by deficiency of specific NER enzymes (XPA-XPG) and is characterized by premature aging and high skin cancer incidence." (PMID 31779194, 2019). "For example, certain forms of ataxia are caused by mutations in the BER-associated gene APTX, and mutations in NER-related genes (XPA-XPG) result in xeroderma pigmentosum, both syndromes that are accompanied by higher rates of neurodegeneration." (PMID 28218666, 2017). "Next, we assessed the effects of silibinin on dermal fibroblasts from xeroderma pigmentosum patients deficient in XPA or XPB." (PMID 26447614, 2015). "This might explain the phenotype of the XPA-associated Xeroderma pigmentosum (XP) patients with mostly milder neurological and clinical phenotypes." (PMID 39021334, 2024). "Mutations in the XPA gene lead to the most severe forms of xeroderma pigmentosum." (PMID 39062528, 2024). "These lead to the suppression of the recruitment of NER-associated factors (e.g., xeroderma pigmentosum groups A (XPA) and xeroderma pigmentosum groups F (XPF)), dramatically inducing excessive accumulation of Pt-DNA adducts and the apoptosis of Pt-resistant tumour cells." (PMID 36450764, 2022). "PARP1 may be associated with xeroderma pigmentosum, complementation group A through interactions with XPA, and the related susceptibility to skin cancer." (PMID 34220964, 2021). "TTD is a distinct condition from Xeroderma Pigmentosum (XP) caused by mutation in eight XP‐associated genes: XPA, XPD (ERCC2), XPB (ERCC3), XPF (ERCC4), XPG (ERCC5), XPC, XPE (DDB2), and a variant form related to the POLH gene." (PMID 39976384, 2025). "Xeroderma pigmentosum (XP) is a rare autosomal recessive disease caused by pathogenic variants in seven nucleotide excision repair genes (XPA to XPG) and POLH involved in translesion synthesis." (PMID 39621777, 2024). "Mutations in genes XPA to XPG can cause xeroderma pigmentosum (XP), whereas mutations in CSA and CSB can cause Cockayne syndrome (CS) or, together with mutations in UVSSA, UV-sensitive syndrome." (PMID 38664429, 2024). "Patients with reported mutations in the XPA gene experience some of the most severe phenotypes of a disease called xeroderma pigmentosum (XP) and are at a significantly increased risk for skin cancer." (PMID 32170071, 2020). "Xeroderma pigmentosum (XP) is a genetically and clinically heterogeneous disease, associated with an inherited defect in one of eight different genes (XPA to XPG and XPV)." (PMID 29208038, 2017).
xeroderma pigmentosum (continued). "The best known example is Xeroderma Pigmentosum (XP) and its seven XPA to XPG subgroups corresponding to the associated mutated NER enzyme." (PMID 26263968, 2015). "In humans, hereditary defects in NER are implicated in several autosomal recessive disorders, including xeroderma pigmentosum (XP); seven XP-related genes, XPA through XPG, encode proteins that play crucial roles in the human NER pathway." (PMID 26042670, 2015). "These diseases include xeroderma pigmentosum (XP) which is due to a defect in one of approximately eleven XP associated genes (including XPA, ERCC3 (XPB), XPC, and POLH (XPV))." (PMID 23285288, 2012). "The Xeroderma pigmentosum group A protein (XPA) is one of eight factors that were found to be deficient in XP disorders, and the XPA-deficient cells exhibit the highest UV sensitivity among the XP cells." (PMID 22174788, 2011). "In humans, mutations in the gene encoding for xeroderma pigmentosum group A (XPA), a vital part of the nucleotide excision repair (NER)-repair system, result in xeroderma pigmentosum." (PMID 38257148, 2024). "Rare germline variants in ERCC3, XPA, and XPC are related to xeroderma pigmentosum, a disease that increases the appearance of ultraviolet-induced skin cancer at an early age." (PMID 39408606, 2024). "We also measured cell viability in XP2OS cells derived from an XPA mutant xeroderma pigmentosum patient and found that they showed significant and dose-dependent sensitivity to CDEAH." (PMID 37554969, 2023). "In addition, several essential NER genes associated closely with xeroderma pigmentosum (XP) are XPA, XPB, XPC, XPD, XPE, XPF, and XPG, respectively." (PMID 38089451, 2022). "Only BRCC3 (p-value log(−10) = 1.87), WRN (p-value log(−10) = 2.09), USP45 (p-value log(−10) = 1.52) and the xeroderma pigmentosum complementation group A (XPA; p-value log(−10) = 1.32) were significantly upregulated." (PMID 36010871, 2022). "Xeroderma pigmentosum (XP) is a rare autosomal recessive disorder caused by changes in the DNA repair pathway related to variants in eight genes, and it is clinically recognized as XPA, XPB, XPC, XPD, XPE, XPF, XPG, and XPV." (PMID 32935933, 2020). "The NER pathway is a complicated multistep process involving multiple proteins, including replication protein A (RPA) and xeroderma pigmentosum group proteins such as XPA and XPC26." (PMID 28074905, 2017). "Xeroderma pigmentosum (XP) patients exhibited several neurological symptoms such as microcephaly, mental retardation and deafness, which are linked to mutations in genes such as XPA, XPB, XPD, XPF, and XPG that are involved in nucleotide excision repair (NER)." (PMID 27164092, 2016). "Neurological abnormalities are observed in patients from certain xeroderma pigmentosum complementation groups including XPA, XPB, XPD, and XPG." (PMID 26874523, 2016). "Results showed that post-UVB silibinin treatment accelerates DNA repair via activating the NER pathway including the expression of XPA (xeroderma pigmentosum complementation group A), XPB, XPC, and XPG." (PMID 26447614, 2015). "Seven XP(xeroderma pigmentosum) complementation groups have been identified, from XPA to XPG, representing the malfunctioning proteins in the NER mechanism." (PMID 24802942, 2014). "In previous studies we have used xeroderma pigmentosum complementation group A (XPA) as a loading control for nuclear extracts because the expression of this protein generally showed little change under a variety of experimental conditions." (PMID 22559742, 2012). "SIRT1 also regulates other DNA repair pathways, viz. base-excision repair (BER) and nucleotide-excision repair (NER) through the transcription of xeroderma pigmentosum (XPA, XPC) group proteins." (PMID 22247744, 2011). "Indeed, XPA variants are associated with Xeroderma pigmentosum (XP, MIM #278700)." (PMID 40208338, 2025). "The xeroderma pigmentosum group A (XPA) protein plays an essential role in the NER process." (PMID 36496984, 2022).
xeroderma pigmentosum (continued). "Mutations in seven well characterized NER genes (XPA to XPG), including DDB2 (XPE), result in Xeroderma Pigmentosum (XP), a recessive inherited syndrome characterized by heightened UV-sensitivity, neurological abnormalities, and an increased susceptibility to develop skin cancers." (PMID 24489677, 2014). "The association is likely attributed to FOXE1 rather than XPA which is involved in DNA excision repair and the skin disease xeroderma pigmentosum." (PMID 23251661, 2012). "Thus, downregulation of SIRT1 significantly sensitized cells to UV irradiation through interaction with xeroderma pigmentosum group A (XPA), a core factor essential for NER." (PMID 22247744, 2011). "Other pathogenic variants were present in FANCE, XPA and ERCC5, associated with Fanconi anaemia, xeroderma pigmentosum (XP) group A and XP group G, respectively." (PMID 39315505, 2025). "Preclinical studies targeting several enzymes within the NER pathway, including excision repair cross-complementation group 1/xeroderma pigmentosum group F (ERCC1/XPF) and ERCC1/XPA, have demonstrated anti-tumor activity." (PMID 38730598, 2024). "The XPC, XPD and XPA complementation groups present the most frequent forms of Xeroderma pigmentosum in Europe, North Africa, Japan and the USA, as they are responsible for about 90% of XP patients worldwide." (PMID 29208038, 2017). "The deficiency of specific proteins can lead to specific diseases; for example, XPA, XPB, XPC, XPD, XPE, XPF and XPG are derived from xeroderma pigmentosum and belong to the GG-NER sub-pathway, while CSA and CSB proteins are associated with Cockayne syndrome, which belongs to the TC-NER sub-pathway." (PMID 36290563, 2022). "Biallelic pathogenic variants in one of the seven NER genes coding for the so-called complementation groups, XPA, ERCC3, XPC, ERCC2, DDB2, ERCC4, ERCC5, the NER gene ERCC1, and the gene coding for XP variant, POLH, are the causes of the rare hereditary disease Xeroderma pigmentosum (XP)." (PMID 35174087, 2022). "The pathway requires over 30 proteins, including the XPA through XPG proteins, that are defective in patients with the disease xeroderma pigmentosum (XP)." (PMID 26559971, 2016). "Furthermore, they examined the repair process in a Xeroderma pigmentosum (XP) patient derived cell line, lacking the XPA protein, which is crucial for repair of UV induced DNA damage." (PMID 37467630, 2023). "However, depletion of HBO1 in cells derived from xeroderma pigmentosum patient complementation groups, XPE, XPC and XPA, did not lead to additional sensitivity towards ultraviolet irradiation." (PMID 28719581, 2017).
lung carcinoma (15 papers, 2003 to 2024). "XPA rs1800975 polymorphisms have been reported to be associated with susceptibility in lung cancer patients." (PMID 38137354, 2023). "The genomic variabilities of XPA rs2808668 are also considered to jointly contribute to lung cancer risk." (PMID 38137354, 2023). "For example, the XPA rs1800975 polymorphism was reported to be related to the risk of lung cancer in Norwegian, Germany or Korean populations but not in patients from Belgium or the USA." (PMID 32435155, 2020). "Homozygous carriership of the XPA gene variant rs1800975 in patients with advanced lung cancer treated with platinum-based regimens is associated with shorter survival." (PMID 26019482, 2014). "A polymorphism in the 3′ UTR of ERCC1 (not the exon 4 RFLP studied here) has been associated with glioma and SCCHN and two XPA polymorphisms are associated with lung cancer." (PMID 12865926, 2003). "Although we observed a group of publications regarding the influence of XPA rs1800975 on the risk of certain specific cancers, such as lung cancer, head and neck cancer, breast cancer, and digestive system cancer, the evaluation strategies, study number and statistical power differed." (PMID 32435155, 2020). "Therefore, XPA rs1800975 AA genotype was recognized as a risk factor for lung cancer." (PMID 27768589, 2016). "XPA is involved in several cisplatin-resistant cancers such as gastric cancer, germ cell tumors, prostate cancer, and lung cancer." (PMID 36509750, 2022). "In lung cancer (LC) cell lines, in which endogenous XPA levels are higher, inhibition of HIF-1α reduces the expression of XPA, while in LC cell lines with lower endogenous XPA, hypoxia elevates expression of HIF-1α and XPA." (PMID 32235701, 2020). "Early studies identified associations with lung cancer risk in selected mutated NER genes (ERCC1-6, LIG1, POLE, XPA, and XPC genes)." (PMID 30181806, 2018). "It has been proved that polymorphisms of DNA repair genes, such as the polymorphisms of XPA ‐4G>A (rs1800975), ERCC2 862G>A (rs1799793) 12, MSH3 3133G>A (rs26279), and PMS1 639G>A (rs5742938) 13, are associated with the risk of lung cancer." (PMID 27335251, 2016). "Taking these data together, we conclude that upregulated NER capacity in preconditioned lung cancer cells is caused partly by an increased level of SIRT1, which modulates XPA sensitivity to DNA damage." (PMID 26317794, 2015). "While other genetic mutations within XPA, appeared to serve as protective factors against lung cancer (for nonsmokers) and gastric cancer." (PMID 38686623, 2024). "Collectively, this evidence did not support the strong association between lung cancer risk and XPA rs1800975." (PMID 32435155, 2020). "XPA has been reported to correlate with cisplatin cisplatin resistance in lung cancer cell lines." (PMID 26156020, 2015). "This ability of isolated and washed importin-α4 to bind recombinant XPA was observed for both H1299 lung carcinoma and GM04429 transformed fibroblast cells, and suggests that this behavior is a general feature of the XPA-importin-α4 interaction." (PMID 23861882, 2013). "Down-regulating XPA expression or expressing a competitive, nonfunctional truncated XPA decreases the platinum resistance in lung cancer and prostate cancer DU15 cell lines, but not in prostate cancer PC3 cells." (PMID 26156020, 2015).
skin cancer (14 papers, 2015 to 2025). "Our findings provide evidence of the close relationship between the XPA rs1800975 A/G polymorphism and susceptibility to skin cancer in the Caucasian population." (PMID 32435155, 2020). "To summarize, our comprehensive integrative analysis data demonstrated statistical evidence on the association between the XPA rs1800975 A/G polymorphism and susceptibility to skin cancer, especially skin BCC, in the Caucasian population." (PMID 32435155, 2020). "The importance of the XPA factor is evident in patients harboring mutations in the gene as they have a skin cancer prone phenotype; and also XPA −/− mice are prone to skin tumors development." (PMID 26447614, 2015). "Therefore, the Xeroderma pigmentosum patients deficient in DDB2, XPC, and XPA genes are highly cancer prone and display over 2,000-fold increased incidence rates of skin cancer due to defects in NER pathway." (PMID 27442013, 2016). "Accordingly, all five specific skin cancer genes from the NER class - DDB2, ERCC3, ERCC5, XPA, and XPC - are associated with UV-sensitive skin." (PMID 26856619, 2016). "Additionally, XPA deficiency is known to decrease antioxidant defense and increase susceptibility to UVB-induced skin cancer." (PMID 29213352, 2017). "Dietary GSPs do not have the ability to inhibit UVB-induced skin tumor development in XPA-deficient, i.e., NER-deficient mice, but have the ability to inhibit UVB-induced skin tumor development in their wild-type counterparts." (PMID 28548949, 2017). "Our data from the pooling analysis, FPRP analysis and TSA demonstrated a significant difference between skin cancer cases and negative controls under six genetic models, suggesting the contribution of the G allele within XPA rs1800975 to an enhanced susceptibility to skin cancer." (PMID 32435155, 2020). "Furthermore, dietary GSPs significantly inhibited UVB-induced skin tumor development in wild-type mice but not in XPA-deficient mice." (PMID 28548949, 2017). "In contrast, dietary GSPs did not significantly inhibit UVB-induced skin tumor development in XPA-KO mice as compared to tumor development in XPA-KO mice that were not provided as GSPs-supplemented diet." (PMID 28548949, 2017).